CCL19 (C-C motif chemokine ligand 19)
Diseases named in the same sentence as CCL19 in open-access papers (continued):
Sharing a sentence is not in itself a finding about the gene and the disease.
cancer (continued). "Our study aims to comprehensively evaluate the prognostic relevance of CCL19 expression in various cancer types." (PMID 37944262, 2023). "This suggests the potential of CCL19 as a prognostic marker, predictive biomarker for immunotherapy, therapeutic target of cancers." (PMID 37944262, 2023). "CCR7 (C-C Motif Chemokine Receptor 7), a receptor of cytokines CCL19 and CCL21, is implicated in the homing of T cells in lymph nodes, and it has mostly been studied with regard to its proangiogenic effect on cancer cells through an increase in VEGF levels." (PMID 38153746, 2023). "Specifically, the absence of molecular experiments to validate the biological significance of CCL19 in cancer cell malignancy is notable." (PMID 37944262, 2023). "In a broader pan-cancer context, we explored the correlation between CCL19 expression levels and various immune cell types." (PMID 37944262, 2023). "CCL21 and CCL19 were highly expressed in Mel94, which assisted in immunotherapy of cancers by potentiating immune response." (PMID 35646893, 2022). "CCR7 binds to the CCL19 and plays an important role in the trafficking of immune cells as well as cancer metastasis." (PMID 36199375, 2022). "The aim of this study was to assess the expression of CCR7/CCL19 in cancer tissue in relation to that of miRNAs (miR-let-7a, miR-335) as transcriptional regulators." (PMID 35160116, 2022). "CD6, CCL19, CD40LG, XCR1, MAGEA1, ATM and CCL19 genes were significantly differentially expressed in MET-altered cancers." (PMID 33437521, 2020). "Here, we observed that the serum levels of various chemokines, including CCL19, IL-8, CXCL1, CXCL12, and RANTEs, the latter of which has been associated with the recruitment of Tregs in cancer patients, were increased in BC patients." (PMID 30718502, 2019). "CCR7-expressing cancer cells are also recruited by CCL19 and CCL21 to metastasize in lymphoid organs." (PMID 30518137, 2018). "The chemokine receptor CCR7 and its chemokine ligands CCL21 and, less so, CCL19, recruit circulating metastatic cancer cells to lymphatic tissue." (PMID 28841151, 2017). "It is well known that CCR7-expressing cancer cells exhibit high lymphatic invasion ability due to the chemotactic effect of its ligands CCL19 and CCL21 which predominantly expressed in lymphatic endothelial cells." (PMID 24915301, 2014). "Exposure of CXCR4+CXCR7+ cancer cells to CXCL12 greatly potentiated their TEM towards the chemokines CCL19 and CXCL13." (PMID 21672222, 2011). "The F_6 CCL19+ fibroblasts have been shown to interact with T-cells via CXCL12/CXCR4 and F_8 MMP1+ myofibroblasts (myoF) have recently been linked to an immunosuppressive neighborhood in cancer." (PMID 41438752, 2025). "Moreover, the CCR7 chemokine axis, which encompasses CCL21 and CCL19, has emerged as a promising target for cancer immunotherapy, demonstrating potential as a target for therapeutic intervention." (PMID 39505867, 2024). "Of the two ligands of CCR7, CCL19, and CCL21, only CCL21 is associated with metastasis, contributing to lymphatic metastasis in pancreatic, lung, breast, and other cancers via ERK signaling." (PMID 39114657, 2024). "Significantly down-regulated genes in cancer tissue, compared to normal tissue included PLA2G2A, MUC4, PCK1, TXNIP, and genes encoding the CCR7 ligands, CCL19 and CCL21, which are lymphoid chemokines involved in the chemotaxis of lymphoid cells such as leukocytes and dendritic cells." (PMID 38505585, 2024). "Notably, prior studies have unearthed compelling evidence linking low CCL19 expression to unfavorable outcomes in cancers such as small cell lung cancer and follicular lymphoma." (PMID 37944262, 2023). "In light of these insights, we venture to speculate that CCL19 expression levels may bear a significant relationship with the prognosis of cancer patients." (PMID 37944262, 2023).
cancer (continued). "Additionally, the intricate chemokine receptor 7 (CCR7) chemokine axis, characterized by chemokine ligand 21 (CCL21) and CCL19, has emerged as a promising avenue in cancer immunotherapy." (PMID 37944262, 2023). "To achieve this objective, we initiated our investigation by examining the association between CCL19 expression levels and the overall survival (OS) and progression-free survival (PFS) among patients diagnosed with distinct cancer types." (PMID 37944262, 2023). "Besides, six factors had inverse causal associations with cancer, including CCL15, CCL18, CCL19, CCL20, CCL21, and CCL28." (PMID 38075694, 2023). "An effect on cancer survival was only found for plasma CCL19, especially for ER-positive patients." (PMID 36685922, 2022). "In BC, however, CCL19 appeared to play a role as a cancer-promoting gene." (PMID 36581948, 2022). "This may also be the reason why relatively few statistically significant results were obtained regarding the relationship between the expression level of CCR7/CCL19 mRNA, study miRNAs, and cancer features." (PMID 35160116, 2022). "Modulating the function of the CCL19/CCL21/CCR7 axis may hold therapeutic potential for cancer as well as many inflammation‐related diseases, and there are several clinical trials currently underway." (PMID 35702353, 2022). "It was reported that CCL19/CCR7 responded for the migration of cancer calls via the AKT pathway." (PMID 28378417, 2017). "Considerable studies have focused on the potential role of CCL19/ CCR7 axis in several cancers." (PMID 29088748, 2017). "Recent literatures have identified the interaction between CCL19 and human cancer cells." (PMID 29088748, 2017). "In fact, CCL19 has already been found to be overexpressed in various carcinomas." (PMID 29088748, 2017). "The exact mechanism should be tested in various cell lines and confirmed in vivo but there seems to be a trend across cancer types that CCL19 may potentially drive metastasis." (PMID 24762633, 2014). "Cell invasion, which is required for cancer cells to move across physiological barrier, and anti-anoikis, which is essential for cancer cells to survive in circulation system, is significantly enhanced by CCL19 stimulation." (PMID 24915301, 2014). "Based on these properties, we speculated that CCL19 would be an important protein for evaluation in cancer immunotherapy." (PMID 16598185, 2006). "Our findings show that CCL19 may serve as a potential immune stimulator and provide a strong rationale for the evaluation of CCL19 in cancer immunotherapy." (PMID 16598185, 2006). "Together the data suggest that including a secretion signal to pDNA-encoded neoepitopes does not impact the vaccine’s efficacy, while the introduction of a covalent connection between CCL19 and the cancer neoepitopes might favor early induction of C1-specific CD8+ T cells." (PMID 37720215, 2023). "In the VPP cancers, significant increases were observed in CXCL1, CXCL2, GZMB, IL6, CCL13, and CCL19, among others." (PMID 40361362, 2025). "In pan-cancer CAF atlas, we annotated the CAF subpopulation which highly expressed chemokines (CCL19, CCL21 and CXCL2) as inflammatory CAF (iCAF), likely to the previously reported iCAFs." (PMID 39703515, 2024). "By evaluating the spatial co-localization patterns of TLS-enriched cell types in other cancer types, we confirmed the co-localization of TLS-enriched cell types including LAMP3+ DC, Treg, plasma cell, and CCL19+ fibroblast across multiple cancer types." (PMID 38744958, 2024). "As a result, CCL19/CCR7 is crucial for the immune system’s control of inflammatory bowel disorders, infection prevention, and cancer suppression." (PMID 38882664, 2024). "We investigated the therapeutic effects of next-generation chimeric antigen receptor (CAR) T cells producing IL7 and chemokine (C–C motif) ligand 19 (CCL19; referred to as 7 × 19 CAR-T) in these intractable cancers." (PMID 39240078, 2024).
cancer (continued). "CCL19, CCL21, and CCL25 promote lymphoid tissue formation, resulting in the priming and activation of effector T cell responses to cancer-specific antigens." (PMID 39235457, 2024). "This phenomenon is primarily attributed to CCL19’s ability to activate immune cells, such as CD8+ T cells, which subsequently engage cancer cells, leading to apoptosis." (PMID 37944262, 2023). "CCR7, coupled with its natural ligands CCL19 and CCL21 (the CCL19/21-CCR7 axis), controls the trafficking of DCs and metastasis and invasion of some malignant tumor cells." (PMID 37198402, 2023). "Regarding the histopathological type of cancer, a higher CCR7 and CCL19 mRNA expression level was observed in the AC group compared to the SCC group." (PMID 35160116, 2022). "Chemokine ligand 19 (CCL19) is one of the ligands of chemokine receptor 7 (CCR7) and plays an important role in cancer." (PMID 36510567, 2022). "TLS in other cancers have been identified and defined by expression of a number of chemokines that are involved in TLS neogenesis: CCL19, CCL21, CXCL12, CXCL13, CCL17, and CCL22." (PMID 34943886, 2021). "Hypoxia promoted cancer cell production of more macrophage chemokines, and among all increased chemokines (CCL2, CCL5, CCL8, CCL19, CCL21, and CXCL1), CCL8 was the most increased according to qRT-PCR detection." (PMID 31263103, 2019). "We demonstrate that fluorescently tagged CCL19 and CCL21 permit the visualization and quantification of chemokine gradients in real time, while CCR7-expressing leukocytes and cancer cells sense the guidance cues and migrate along the chemokine gradients." (PMID 30518137, 2018). "Although several chemokines, such as CCL4, CCL19, CCL21, CXCL2 or CXCL12, were upregulated at the invasive border than cancer centre, expressions of their receptors were very low in PTC, except for CXCL12 receptor." (PMID 28489070, 2017). "We were interested in how CCL19 and AL10 modulated cyclin D1 expression because this oncoprotein is overexpressed in many cancers and is a potential target for cancer treatment." (PMID 24915301, 2014). "Normally, CCR7 activity is regulated by CCL19 and CCL21, which is secreted by cancer cells themselves and allows cancer cells to migrate to the lymphoid tissues." (PMID 22251626, 2012). "We speculate that RANBP17 may suppress stromal CXCL13, CCL19 and CCL21 through exosome‐mediated mechanisms by reprogramming the cargo of cancer‐derived exosomes to include regulatory RNAs and proteins." (PMID 41397929, 2025). "In support of our hypothesis, we found significantly higher numbers of FRC-like fibroblasts expressing CCL19 and CCL21 in immune-hot HPV+ve cancers." (PMID 39757146, 2025). "Researchers transplanted collagen sponge scaffolds containing LTα1β2, CCL19, CCL21, CXCL12, CXCL13, and soluble RANK ligands, which over time resulted in the development of immune-competent artificial TLSs with potential applications for cancer treatment." (PMID 39840050, 2024). "Other chemokines, including CXCL4, CCL19, and CXCL10, may aid in recruiting immune cells, increasing their cytotoxicity against cancer cells, and inducing apoptosis of malignant cells." (PMID 38475811, 2024). "Intriguingly, CCL19 expression levels exhibited stage-dependent variation, with the lowest expression observed in stage 4, suggesting a potential negative correlation between CCL19 expression and cancer severity." (PMID 37944262, 2023). "Despite the potentially lower expression levels, CCL19 performed as the best APC-binding molecule when combined with 5 CT26-predicted neoepitopes and, therefore, was selected to further develop an APC-targeted TCV for cancer neoepitopes." (PMID 37720215, 2023). "CCL5, XCL1, XCL2, CCL17, CCL22, and CCL19 showed a positive correlation with DEF6 in most cancers, and DEF6 may function in regulating these chemokines in cancer." (PMID 36686789, 2022).
cancer (continued). "It should be noted that the role of CCL19/CCR7 in NSCLC appears to be complex, and post-transcriptional regulation of these genes may be important in the progression and metastasis of this cancer." (PMID 35160116, 2022). "It suggests that SAA1, CXCL10, CCR5, CCL19, CXCL11, CXCL13, and CCL5 have important function in immunotherapy for cancer patients, and may be used as key regulator genes of immunotherapy." (PMID 34093667, 2021). "Similarly, LECs express a high level of the CCR7 ligands CCL19 and CCL21, and COX-2-induced upregulation of CCR7 in cancer cells promotes the migration of cancer cells toward LECs, enhancing lymphatic invasion." (PMID 33203856, 2020). "However, the same chemokines recruit cells that promote the development of cancer, for example CCL17/TARC and CCL22/MDC, CCL20/LARC or CCL19/ELC and CCL21/SLC." (PMID 32781743, 2020). "Data of Wiley and colleagues further indicate that CCL21, and not CCL19, preferentially mediates lymph node metastasis of cancer cells." (PMID 23667660, 2013). "RT-PCR results showed that the expression levels of CCL19, CD24, and ZIC2 were significantly higher in the MCF-7, ZR-75-1, and SK-BR-3 cell lines compared to the reference MCF-10A group, whereas the transcription level of CEBPD was significantly lower in the cancer cell lines (p < 0.05)." (PMID 40895068, 2025). "Thus, we are going to construct the fourth-generation CAR-T cells to secrete a PD-1- or/and CTLA-4-blocking scFv together with IL-7 and CCL19, which may maximize the efficiency of CAR-T therapy for malignant solid tumors." (PMID 36479116, 2022). "The significant KEGG pathways are chemokine signaling pathway (CCL5, CCL18, CCL19, CCL21, CXCL12, CXCL14, CXCL13), ​​NF-kappa B signaling pathway (CCL19, CCL21, CXCL12), intestinal immune network for IgA production (TNFRSF17, CXCL12), pathways in cancer (IGF1, CXCL12)." (PMID 35486660, 2022). "However, in Alizadeh lymphoma dataset and Rosenwald multi-cancer dataset, the expression level of CCL19 was showed no statistical significance between FL samples and normal tissue." (PMID 34544443, 2021). "The discovery that cancer cells overexpress C-C Chemokine receptor 7 (CCR7), which directs them to organs that express their ligands CCL21 and CCL19, led to an increase in reports confirming that chemokine receptors were present in a non-random manner in many other cancers." (PMID 32340161, 2020). "For example, CCL21 (CC chemokine ligand 21) and CCL19 (CC chemokine ligand 19) recruit antigen-presenting dendritic cells and naïve T-cells to the lymph nodes and are thought to play a role in lymph node metastasis of CCR7 (CC chemokine receptor 7)-expressing cancer cells." (PMID 28841151, 2017). "Also in human hepatoma cancer chronic hypoxia cells do not increase CCL19/ELC expression." (PMID 32781743, 2020). "Surprisingly, despite a clear activation of the non-canonical NF-κB pathway in the cancer cells tested, they did not secrete the chemokines CXCL12, CXCL13, CCL19 and CCL21, known to be induced as a consequence of activation of this signaling pathway upon LTβR stimulation of other cell types." (PMID 39215104, 2024). "Likewise, CCL19 was not required for dendritic cell migration from the skin, full dendritic cell maturation and efficient T lymphocyte priming suggesting that CCL21 is the critical CCR7 ligand regulating dendritic cell homeostasis and function in vivo, which may also belong to cancer metastasis." (PMID 23667660, 2013).
infection (103 papers, 2007 to 2025). The state of being infected such as from the introduction of a foreign agent such as serum, vaccine, antigenic substance or organism. "Results showed that MUC5AC, FGB, and CLDN18 were highly expressed only in the control group and L3 infection group, while CCL19 exhibited higher expression levels in the infection groups." (PMID 40979361, 2025). "CCL19 plays a role in attracting immune cells to the site of inflammation or infection in general, and this has been shown in the presence of A. fumigatus as well." (PMID 38407673, 2024). "Further evidence for the ability of TRCs to regulate T cell responses during infections is shown by the ablation of the innate immunological sensing adaptor MyD88 in Ccl19-Cre+ cells in murine Peyer’s patches." (PMID 38038708, 2024). "The RNASeq analyses of MDMs were validated using quantitative RTPCR based on CCL19, highly induced in the presence of hSAA-1, CSF-2, induced after infection with tubercle bacilli, and CXCL8, induced in the presence of either stimuli." (PMID 37781389, 2023). "From the reduced accumulation of rpoB-H445Y Mtb in the DLNs early in infection and the decreased chemotactic sensitivity of infected BMDCs to CCL19, DCs infected with rpoB-H445Y Mtb likely have diminished expression of the cognate receptor, CCR7." (PMID 37682004, 2023). "Some up-regulated genes at 21 dpi (e.g., Ltf, Cxcl9, Pglyrp1, Prg2, Cxcl13, Cxcl3, Ccl9, Ccl19, Krt5, Krt14, Krt15, Krt17, and Slpi) were also identified in a previous infection study by using H1N1(PR8)." (PMID 38005876, 2023). "The infection of Ccl19-Cre Il7fl/fl mice with C. rodentium further showed shortened colon length and increased bacterial concentration in the faeces and colon." (PMID 35440118, 2022). "CCL19, a CC chemokine that induces migration of head kidney leukocytes and increases host immune response, was found up-regulated after the infection with the high virulent virus." (PMID 35215144, 2022). "As expected, TN were refractory to direct cis infection of HIV-1BaL using either PHA/IL-2- or CCL-19-conditioned medium, while total CD4+ T cells were susceptible to productive cis infection." (PMID 33688006, 2021). "In conclusion, smaller B cell follicles together with reduced expression of IL-23, CXCL13 and CCL19 indicate that ELS formation in response to H37Rv infection is impaired in the male lung." (PMID 32198367, 2020). "During WNV infections, CCR7+ DCs regulate the homing of T cells expressing the cognate ligands CCL19 or CCL21 into the lymph nodes immediately following infection and restrict leukocyte migration into the brain." (PMID 31632965, 2019). "Various chemokine genes, responsible for the control and recruitment of immune cells to the site of infection (i.e., Ccl2, Ccl4, Ccl5, Ccl7, Ccl8, Ccl12, and Ccl19), were also significantly upregulated in the VACV-Wyeth infected brains on 4 d.p.i." (PMID 30759813, 2019). "Accordingly, we found increased RNA abundance of Arg1, Socs1, Sra1, Saa1, Ciita, Marco, Mgl2, Cd209d, Cd209e, Cd209f, Ccl1, Ccl11, Ccl17, Ccl19, Ccl20, Ccl22, and Ccl24 genes in Stat2−/− mice when compared to WT mice during super-infection." (PMID 30337919, 2018). "In the present study, CCL19 has also been found upregulated in both organs after the infection with the high virulent virus." (PMID 30065724, 2018). "Increased accumulation of the chemokines chemokine (C motif) ligand 1 (Xcl1), chemokine (C-C motif) ligand 5 (Ccl5), and chemokine (C-C motif) ligand 19 (Ccl19) have been observed in infection." (PMID 28075380, 2017). "While not all donors required CCL19 to facilitate direct infection of resting CD4+ T-cells, adding CCL19 ensured consistent infection of resting CD4+ T-cells in vitro." (PMID 27383184, 2016). "Some studies, but not all, report that pre-conditioning resting CD4+ T-cells with the chemokine CCL19 enhanced direct infection of resting CD4+ T-cells in vitro." (PMID 27383184, 2016).